DLL1 (delta like canonical Notch ligand 1)
Diseases named in the same sentence as DLL1 in open-access papers (continued):
Sharing a sentence is not in itself a finding about the gene and the disease.
melanoma (4 papers, 2011 to 2024). A malignant, usually aggressive tumor composed of atypical, neoplastic melanocytes. "DLL4-Fc induced the expression of NOTCH3 mRNA in the metastatic melanoma cell lines WM852 and WM165, while DLL1 induced NOTCH3 only in WM165." (PMID 37971882, 2024). "Interestingly, the full-length Notch3 receptor level was also increased by DLL1-Fc and DLL4-Fc treatments, which together with the observed increase in the mRNA levels suggest that Notch3 is induced through an autoregulatory loop in the melanoma cells." (PMID 37971882, 2024).
chronic heart failure (3 papers, 2020 to 2023). "Serum DLL-1 levels are significantly higher in patients with chronic heart failure than in healthy individuals, and DLL-1 levels have been significantly associated with diastolic dysfunction, decreased exercise capacity, increased levels of C-reactive protein (CRP), and adverse." (PMID 36036015, 2022). "There have been studies describing DLL1 diagnostic performance for infectious and inflammatory diseases such as meningitis, COPD, or congestive heart failure." (PMID 37298115, 2023). "In infections and rejections following heart transplantation, DLL1 was also described as marker within patients suffering from chronic heart failure or dilatative cardiomyopathy as well as non-small cell lung cancer (NSCLC) and chronic obstructive pulmonary disease (COPD)." (PMID 33142943, 2020).
H1N1 influenza (3 papers, 2011 to 2018). "A dependency of DLL1 transcription on STAT family members was reported previously in Influenza A Virus (H1N1) infection." (PMID 30042932, 2018). "Our recent study also revealed that Dll1 expression on macrophages is dependent on type-I IFN pathways, and is critical for protection against influenza virus A (H1N1) infection." (PMID 23386849, 2013). "However, Dll1 expression was not upregulated following H1N1 influenza stimulation in lung epithelial and fibroblast cell lines (data not shown)." (PMID 22072963, 2011).
Intellectual disability (3 papers, 2022 to 2025). "The key role of DLL1 is supported by cases with brain anomalies, intellectual disability and pathogenic variants in DLL1 gene." (PMID 36246626, 2022). "Disorders linked to DLL1 (OMIM: 618709) exhibit diverse neurodevelopmental symptoms, including developmental delays, intellectual disabilities, autism, attention deficits, stereotypical behaviors, and brain anomalies like hydrocephalus and dysplasia." (PMID 41190327, 2025). "Overlapping microdeletions in the 6q27 region, affecting genes like DLL1, THBS2, PHF10, and ERMARD, linked to developmental delay, intellectual disability, and brain malformations." (PMID 41190327, 2025). "Relevant in this regard, a recent report with human patients shows that DLL1 haploinsufficiency correlates with intellectual disability, autism and seizures, in addition to variable prenatally detected brain malformations." (PMID 36590296, 2022).
multiple myeloma (3 papers, 2010 to 2021). "On the other hand, cancers in which over-expression of Jag1, Jag2, and DLL1 are associated with poor survival, such as prostate and breast carcinomas, CNS tumors, and multiple myeloma, may be tractable targets." (PMID 20161710, 2010). "In multiple myeloma, DLL1-mediated Notch activation has been shown to increase cell proliferation, promote clonogenic growth in vitro, accelerate tumor growth initiation, and contribute to drug resistance." (PMID 31107884, 2019). "p21 is repressed by Notch pathway activation and DLL1-mediated Notch activation increased multiple myeloma cell proliferation by decreasing p21." (PMID 31107884, 2019). "Furthermore, the PD-1-blocking antibody (CT-011, pidilizumab) used to enhance anti-myeloma cytotoxicity responses by NK cells in that report was subsequently found to primarily target the Notch2 ligand, Delta-like 1 (DLL1)." (PMID 33435153, 2021). "This hypothesis is consistent with data showing that DLL1-Notch pathway activation increased the number of colonies of multiple myeloma cells." (PMID 31107884, 2019).
neuroblastoma (3 papers, 2017 to 2019). Neuroblastoma (NB) is the most common solid, extracranial childhood tumor. "In childhood neuroblastomas with MYCN gene amplification, DLL1 is highly expressed and implicated in the onset of this type of cancer by promoting cell proliferation and maintaining their undifferentiated status." (PMID 31107884, 2019). "In particular, we recognized Notch ligand DLL1 as the specific molecular target in childhood neuroblastoma and we proposed miRNAs as novel therapeutic tool to attack “DLL1 positive” neuroblastoma." (PMID 29930753, 2018). "DLL1 mRNA and protein expression levels were measured in three different neuroblastoma cell lines using quantitative real-time PCR and Western Blot analysis, respectively." (PMID 28525978, 2017). "In silico analysis demonstrated that DLL1 is one of the targets of miRNA-34 family members that maps on chromosome regions that are frequently deregulated or deleted in neuroblastoma." (PMID 28525978, 2017). "In conclusion, the data collected point to DLL1 Notch ligand as a new and attractive molecular target in childhood neuroblastoma, and we propose miRNAs as new potential therapy to act on high DLL1 expression." (PMID 28525978, 2017). "Neuroblastoma cells were transfected with miRNA-34 family members, and the effect of miRNAs transfection on DLL1 mRNA expression levels, on cell differentiation, proliferation and apoptosis was measured." (PMID 28525978, 2017). "In the present study Notch ligand DLL1 emerged as a novel molecular target in childhood neuroblastoma and miRNAs could be an innovative tool to attack “DLL1 positive” tumors." (PMID 28525978, 2017). "This study identified Notch ligand DLL1 as a new and specific molecular target in childhood neuroblastoma, suggesting that miRNAs could be a novel therapeutic tool to develop an effective strategy to attack “DLL1 positive” neuroblastoma." (PMID 28525978, 2017). "This study identified the Notch ligand DLL1 as a novel and attractive molecular target in childhood neuroblastoma and its results could help to devise a targeted therapy using miRNAs." (PMID 28525978, 2017). "Our data indicate that, within the miRNA-34 family, miRNA-34b induced significant downregulation of DLL1 mRNA expression levels, cell differentiation and arrested cell proliferation in IMR-32 neuroblastoma cells." (PMID 28525978, 2017). "In this study we further investigated the role of Notch signaling and identified Delta-like 1 (DLL1) as a novel molecular target in neuroblastoma cells with a high degree of MYCN amplification, which is a major oncogenic driver in neuroblastoma." (PMID 28525978, 2017).
retinoblastoma (3 papers, 2016 to 2019). A malignant tumor that originates in the nuclear layer of the retina. "Meanwhile, if oscillatory gene expression in some undifferentiated cells/RPCs does not stop due to pathological events (e.g., mutations in genes regulating the stability of mRNA and proteins of genes like Notch1, Hes1, Dll1, Ascl1, Neurog2, etc.), these cells may begin retinoblastoma formation." (PMID 31607861, 2019). "A series of canonical pathways, including those involved in Rb (Retinoblastoma)/E2F cell cycle (Rb, E2f2, E2f3, E2f5, Cdk6, DHFR), Notch (Dll1, Notch 2, Jag1), Wnt (Wnt, Axin2, Wisp2/Ccn5) and NF-κB (Ikbip) were found to participate in this network." (PMID 30742662, 2019). "Among the DLL ligands, DLL4 mRNA appeared to be highly expressed in both retinoblastoma lines, compared to DLL1 and DLL3, and it was also highly expressed in the non-neoplastic adult retina." (PMID 27661116, 2016).
viral infection (3 papers, 2011 to 2025). "Soluble DLL1 shows promising potential in bacterial sepsis, however, there has been limited research concerning its role in viral infections and viral sepsis." (PMID 40425661, 2025). "Blocking Dll1 during viral infection led to significantly higher mortality and greater accumulation of inflammatory cells in the respiratory tract." (PMID 22072963, 2011).
acute kidney injury (2 papers, 2020 to 2025). Sudden and sustained deterioration of the kidney function characterized by decreased glomerular filtration rate, increased serum creatinine or oliguria. "First, all complicating factors (acute renal failure, acute liver failure, bacterial infection, acute rejection) can induce elevated levels of DLL1." (PMID 33142943, 2020).
Arthritis (2 papers, 2012 to 2021). Inflammation of a joint. "Other Notch member-specific modulations have successfully attenuated experimental arthritis using HMD1-5 hamster anti-mouse Dll1 IgG and anti-human and anti-mouse Notch3 IgG2a mAbs." (PMID 33912195, 2021). "Blockade of Dll1 suppressed the osteoclastogenesis not only in vitro but also in a murine arthritis model." (PMID 22390640, 2012). "Actually, treatment with anti-mouse Dll1 blocking mAb ameliorated K/BxN serum-induced arthritis, a mouse model of RA, and reduced osteoclasts number in the affected joints." (PMID 22390640, 2012). "In order to explore the role of Dll1 at the effecter phase of arthritis, K/BxN serum-induced arthritic mice, a mouse model for RA, were therapeutically treated with anti-mouse Dll1 mAb." (PMID 22390640, 2012). "Actually, blockade of Dll1 ameliorated arthritis induced by K/BxN serum transfer, reduced the number of osteoclasts in the affected joints and suppressed ovariectomy-induced bone loss." (PMID 22390640, 2012). "Actually, arthritis score and hematoxylin and eosin staining demonstrated that anti-mouse Dll1 mAb treatment ameliorated K/BxN serum-induced arthritis as compared to control hamster IgG treatment." (PMID 22390640, 2012). "Endothelial DLL1 is also involved in Notch2-mediated differentiation of the Ly6Clow monocyte subtype, a subtype involved in both initiation and progression of experimental arthritis." (PMID 33912195, 2021). "Notably, blockade of Dll1 with anti-Dll1 mAb in RA model mice ameliorates arthritis and reduces the number of osteoclasts in the affected joints." (PMID 22390640, 2012). "Finally, we showed that blockade of Dll1 could suppress osteoclastogenesis in the affected joints in a murine arthritis model." (PMID 22390640, 2012).
bladder cancer (2 papers, 2012 to 2019). "Recently, mutations in Notch1,2,3 have been described in head and neck cancers and alterations in the expression of DLL1 have been described in several tumors, including oral squamous cell carcinoma and urinary bladder cancer." (PMID 23056603, 2012).
developmental delay (2 papers, 2023 to 2025). "QKI probably has an additive effect on the level of developmental delay next to the deletion of DLL1, which on its own can lead to moderate developmental delay in small (500 kb) deletions." (PMID 36935482, 2023). "Almost all the individuals in our cohort with a deletion including DLL1 had developmental delay." (PMID 36935482, 2023). "Besides DLL1, QKI seems to mark a tipping point in the extent of developmental delay." (PMID 36935482, 2023).
diabetes (2 papers, 2021 to 2022). "In addition, in some diseases associated with diabetes, DLL1 or Notch signaling was found to be more highly expressed in some organs." (PMID 36551281, 2022). "Genes such as KCNE2, DLL1, ACVR1C, RGS3, MLXIPL (MLX interacting protein like), PAG1, SLC2A10 and GRB14 play important role in type 2 diabetes mellitus progression." (PMID 33902539, 2021).
dilatative cardiomyopathy (2 papers, 2020 to 2021). "High levels of Notch ligand Dll1, were found in the serum of patients with HF and, similarly, high levels of Dll1 and periostin, a non-canonical Notch ligand, were found in serum from patients with dilated cardiomyopathy." (PMID 34527667, 2021).
encephalitis (2 papers, 2014 to 2023). An acute inflammatory process affecting the brain parenchyma. "DLL1 levels in cerebrospinal fluid (CSF) and serum of patients with tuberculous meningitis (TBM) were higher than those in the bacterial meningitis, viral meningitis/encephalitis and nondiagnosed groups, indicating that DLL1 may be a new biomarker for TBM diagnosis." (PMID 37063841, 2023).
endothelial dysfunction (2 papers, 2024 to 2025). In vascular diseases, endothelial dysfunction is a systemic pathological state of the endothelium (the inner lining of blood vessels) and can be broadly defined as an imbalance between vasodilating and vasoconstricting substances produced by (or acting on) the endothelium. "It is tempting to hypothesize that the association of DLL1 with adverse outcome in scrub typhus patients may involve a role in promotion of macrophage inflammation and endothelial dysfunction with vascular leakage, two hallmark of severe O. tsutsugamushi infection." (PMID 38502427, 2024).
epilepsy (2 papers, 2025). A brain disorder characterized by episodes of abnormally increased neuronal discharge resulting in transient episodes of sensory or motor neurological dysfunction, or psychic dysfunction. "However, this individual also has a likely pathogenic variant in DLL1 that also is associated with epilepsy." (PMID 39879987, 2025). "A likely pathogenic frameshift variant in DLL1 (MIM: 606582) of unknown inheritance was identified in individual 11, which was previously associated with neurodevelopmental phenotypes (MIM: 618709), including epilepsy and cortical malformations." (PMID 39879987, 2025).
Hydrocephalus (2 papers, 2022 to 2025). Hydrocephalus is an active distension of the ventricular system of the brain resulting from inadequate passage of CSF from its point of production within the cerebral ventricles to its point of absorption into the systemic circulation. "Therefore, mild microcephaly resulting from deficient neurogenesis due to reduced DLL1 levels is a condition that favors hydrocephalus development." (PMID 36590296, 2022). "Our observations suggest that Dll1 haploinsufficiency limits Notch signaling during brain development which, on one hand, leads to reduced brain cell density and causes microcephaly and hydrocephalus phenotypes and, on the other, alters the myelination process after birth." (PMID 36590296, 2022). "Fetuses with reduced transverse cerebellar diameter, hydrocephalus, or bilateral ventriculomegaly should be evaluated for 6q terminal deletions involving DLL1." (PMID 41190327, 2025). "Interestingly, enlarged ventricles (i.e., hydrocephalus) was a common characteristic of brains of Dll1 haploinsufficient mice since early ages." (PMID 36590296, 2022).
Infertility (2 papers, 2019 to 2020). "A recent study has revealed that NOTCH1 and NOTCH ligands including JAG1 and DLL1 are down-regulated in the endometrium of women with unexplained infertility during the implantation window compared with the fertile subjects." (PMID 31168348, 2019).
influenza infection (2 papers, 2011 to 2024). "Treatment of WT mice during influenza infection, with either neutralizing antibodies specific for Dll1 or a γ-secretase inhibitor (GSI), which blocks Notch signaling, resulted in increased mortality, impaired viral clearance, and lower IFN-γ production." (PMID 22072963, 2011). "Together, these results suggest that Notch signaling through macrophage-dependent Dll1 is critical in providing an anti-viral response during influenza infection by linking innate and acquired immunity." (PMID 22072963, 2011). "To directly test the effect of Dll1 against influenza infection, we blocked Dll1 functionality in WT mice by intraperitoneal passive immunization with anti-murine Dll1 Ab." (PMID 22072963, 2011). "Our results further showed that specifically blocking Dll1 during influenza infection impaired the survival and inflammatory status in our model with a decreased number of IFN-γ+CD4+ and IFN-γ+CD8+ T cells." (PMID 22072963, 2011). "Histological assessment showed more severe pneumonia in anti-Dll1-treated mice 7 days post influenza infection." (PMID 22072963, 2011). "Moreover, Notch ligands Dll1 and Jag1 were upregulated on migratory DCs from the lung and draining lymph nodes on influenza infection, which in turn primed naïve CD8+ T cells to assemble a specific virus response." (PMID 39209451, 2024). "Blockage of Dll1 resulted in accelerated inflammatory responses and decreased IFN-γ levels from CD4+ and CD8+ T cells during influenza infection." (PMID 22072963, 2011). "Of the five Notch ligands, Dll1 is the only Notch ligand specifically upregulated on macrophages following influenza stimulation, but it is not expressed on DCs." (PMID 22072963, 2011). "Neutrophils and macrophages are the dominant leukocytes recruited to the lung during an influenza infection, and this process is markedly augmented in both IFNαR−/− mice (data not shown) and WT mice treated with anti-Dll1 Ab." (PMID 22072963, 2011).
liver cancer (2 papers, 2017 to 2024). An epithelial or non-epithelial malignant neoplasm that arises from the liver. "Similar to what was observed in liver cancer stem cells, reduced nuclear translocation of NICD2 was found in Rik-overexpressing CD8+ T cells upon in vitro stimulation with Notch2 ligand DLL1." (PMID 28382040, 2017).
liver fibrosis (2 papers, 2015 to 2021). "Furthermore, Notch ligands (Dll1, Dll4, Jag1) and downstream molecule (Hes1) were also significantly induced in fibrotic mice versus olive-oil treated non-fibrotic control livers signifying the role of Notch pathway in liver fibrosis." (PMID 26658360, 2015). "While in CCl4-induced liver fibrosis mice experiment, JY5 not only decreased the mRNA expressions of Jagged1, Notch2, Notch3, Notch4 and RBP-κB, but also downregulated the expression of Dll1." (PMID 34630075, 2021).
lupus (2 papers, 2020 to 2023). "Based on our findings, we then investigated the therapeutic potential of blocking DLL1 on systemic lesions and renal injury of lupus." (PMID 37915129, 2023).
microcephaly (2 papers, 2022 to 2023). A congenital or acquired developmental disorder in which the circumference of the head is smaller than normal for the person's age and sex. "Brain weight and size of Dll1+/lacZ mice was significantly decreased compared with WT littermates (i.e., microcephaly), a phenotype detected early after birth." (PMID 36590296, 2022). "In agreement with a broad influence of DLL1 in the determination of neuronal density in the brain, mild microcephaly was a penetrant phenotype detected early after birth in Dll1+/lacZ mice." (PMID 36590296, 2022).
Obesity (2 papers, 2014 to 2022). Accumulation of substantial excess body fat. "For several adipokines (ANGPTL3, DLL1, chemerin, clusterin, leptin, Nampt, resistin, GPX3), we identified a close relationship with parameters of obesity (BMI, waist circumference, body fat mass), but also inflammation (hsCrP)." (PMID 24968098, 2014). "By contrast, ECM genes, VEGF signaling members Vegfa and Vegfc and Notch1 signaling genes Dll1, Jag1 and Numb were upregulated by sustained obesity in lung cap ECs but were not attenuated by a reversion diet." (PMID 36400935, 2022). "Since ANGPTL3, DLL1 and GPX3 are found in the same cluster, our data may stimulate further research characterizing the potential role of ANGPTL3, DLL1 and GPX3 in obesity, altered glucose metabolism and inflammation." (PMID 24968098, 2014).
ovarian carcinoma (2 papers, 2022 to 2025). A malignant neoplasm originating from the surface ovarian epithelium. "Ovarian cancer cells express Notch1, Notch2, Notch3, Notch4 and Jagged2, while ECs located in the ovary express Jagged1 and Dll1 and Dll4 ligands." (PMID 36430649, 2022). "A recent analysis of the cancer genome atlas (TCGA) ovarian cancer data, largely comprised of HGSOC samples, has shown a significant reduction in DLL1, JAG1, NOCTH4, and an increase in HES1, NOCTH1 and NOTCH3 expression in OC samples compared to normal tissues." (PMID 40002854, 2025).